RAC1 (Rac family small GTPase 1)
Diseases named in the same sentence as RAC1 in open-access papers (continued):
Sharing a sentence is not in itself a finding about the gene and the disease.
glioma (continued). "RAC1 is also involved in the maintenance of cancer stemness in glioma stem-like cells and in kidney cancer in response to upregulation by a novel oncogenic long noncoding RNA, LncRNA NR2F2-AS1." (PMID 34771704, 2021). "It was also reported that TRPV4 regulates migration and invasion of glioma cells via Rac1 signaling." (PMID 33262217, 2021). "To better understand the upstream signaling pathways of Rac1, we compared the transcriptomic profile of glioma specimens from the lower grade glioma dataset from the Cancer Genome Atlas Program (TCGA)." (PMID 32224866, 2020). "Knockdown of IQGAP1 inhibits both Rac1- and Cdc42-mediated migration and invasion of glioma cells and leads to the suppression of several other components of the invasion process such as MMPs." (PMID 32089990, 2020). "In the SNB19 glioma cell line, knocking down Rac1 leads to a drastic decrease in glioma cell migration and invasion." (PMID 32089990, 2020). "IH Jung and his colleagues studied the role of Rac1 in glioma by generating new zebrafish transgenic lines expressing dominant active forms of Akt1 and Rac1." (PMID 33302361, 2020). "On the other hand, dedicator of cytokinesis 1 (DOCK1), also known as DOCK180, is a Rac GEF which associates with cofactor engulfment and cell motility 1 (ELMO1) overexpressed in glioma cells and activates Rac1." (PMID 32089990, 2020). "NSC23766 is a Rac1 inhibitor that synergistically inhibits glioma cell migration and invasion when used with anti-EGFR drugs." (PMID 32089990, 2020). "The stimulation of PDGFRα by PDGF growth factor leads to the phosphorylation of DOCK1 which, in turn, activates Rac1 and subsequently enhances glioma cell migration and invasion." (PMID 32089990, 2020). "Once overexpressed, it inhibits glioma cell migration and invasion through the inactivation of Rac1." (PMID 32089990, 2020). "Following EGF stimulation, SWAP-70 was detected at the leading edge of migrated glioma cells, accompanied by an increase in Rac1 activity." (PMID 32089990, 2020). "Rac1 is the Rho GTPase family member that is mostly expressed in gliomas, and its level of expression correlates with patient survival outcome." (PMID 32585958, 2020). "Upregulation of Rac1 has been recently reported in various kinds of cancers and is correlated with poor overall survival of patients with glioma." (PMID 32585958, 2020). "Recent findings also reveal the potential role of GTPase Rac1 in the maintenance of stemness and malignancies in glioma stem-like cells." (PMID 32224866, 2020). "Specific inhibition or knockdown of NKCC1 both attenuate activated Rac1 and RhoA, and the pharmacological inhibitions of Rac1 and RhoA both impair the invasion and migration abilities of gliomas." (PMID 30159893, 2019). "NKCC1 inhibition effectively decreased the activation of Rac1 and RhoA, and the pharmacological inhibition of Rac1 and RhoA dramatically impaired glioma invasion and migration." (PMID 30159893, 2019). "Third, we also found that NKCC1 regulated EMT through the Rac1 and RhoA signaling pathways in gliomas." (PMID 30159893, 2019). "Although early studies demonstrated that methuosis can be induced in glioma by overexpressing active forms of Ras or Rac1, more recent studies have identified small molecules that can trigger this form of death in a manner that is independent from Ras or Rac1." (PMID 30909495, 2019). "The mutual inhibition of RhoA and Rac1 is further complicated by Cdc42 being capable of activating Rac1 in glioma." (PMID 31003495, 2019). "In general, increased HA expression is associated with an increase in motility and migration of glioma, probably via a CD44 or RHAMM induced activation of Rho GTPases, such as Rac1 or Cdc42." (PMID 31003495, 2019). "The same is true for glioma cells, showing an increased expression of the mutually inhibiting GTPases RhoA and Rac1." (PMID 31003495, 2019). "Activation of Fn14 enhanced glioma cell invasion and survival, which were mediated, in part, by Rac1 and NF-κB." (PMID 28103571, 2017).
glioma (continued). "Rac1, which promotes invasive glioma cell behavior, can be overexpressed too and can be also activated downstream of signaling networks triggered by Ephrin-B3 ligand, EGFRvIII receptor, or PDGFRα receptor." (PMID 29261132, 2017). "In the central nervous system, Troy functionally replaces p75 to inhibit axon outgrowth via EGFR/RhoA signaling or activates Rac1 to facilitate cell migration in advanced glial tumors." (PMID 28881583, 2017). "TWEAK-Fn14 signaling promotes the activation of Rac1 to regulate glioma cell migration and invasion." (PMID 28103571, 2017). "RhoG, which stimulates lamellipodia formation, is often overexpressed in gliomas; it is also able to activate Rac1, with a further increase in cell migration." (PMID 29261132, 2017). "Studies from other groups revealed that irradiation can lead to an increased motility of glioma cells and it was argued that this effect is related to the activation of the small GTPases Rac1 and subsequent inhibition of RhoA." (PMID 28926987, 2017). "One evidence for the involvement of Rac in glioma progression is the dominant-active Rac1 (DARac1, RacG12V) transgenic zebrafish model." (PMID 28160553, 2017). "Major TGF-Beta-EMT inducing factors (RHOA, RAC1, ROCK2, CDC43 and LIMK1) and EMT transcription factors (TWIST1, SOX9, TRIM28 and SERP2) have among the highest risk scores in our glioma transcriptional model." (PMID 28916782, 2017). "Due to the important role of ARHGDIA in the regulation of Rho GTPase, then how does its decreased expression regulate its effector proteins including Rac1/cdc42 and RhoA in glioma cells?" (PMID 27726098, 2016). "By now, we found that knockdown of ARHGDIA by siRNA resulted in activating the GTPase activity of Cdc42, Rac1, RhoA, and pAkt to promote glioma cell proliferation and migration." (PMID 27726098, 2016). "For example, in glioma cells, the pro-metastatic fibroblast growth factor-inducible 14 (Fn14) can induce its own expression through the activation of Rac1 and NF-κB, thereby promoting tumour cell migration and invasion." (PMID 27191257, 2016). "Together, our analyses show that the protein level of ARHGDIA, which is known to be a negative regulator of Rho GTPases such as Rac1, Cdc42 and Rho, is decreased in glioma tumors compared with control brain tissues." (PMID 26761212, 2016). "This includes effects on cell invasion (RAC1, RAC2, RAC3, RHOA, RHOC), focal adhesion formation (RHOA), stemness of glioma precursor cells (RAC1), cell proliferation (RAC1, RND3) and cell cycle (RND3)." (PMID 26132659, 2015). "Li and Lee found that Sema5A inhibited the Rac1 GTPase through stimulation of plexin-B3, which resulted in the inhibition of glioma cell migration and invasion." (PMID 25780417, 2015). "Based on the culmination of evidence, the treatment of high-grade glioma should focus on targeting Rac1." (PMID 25243137, 2014). "In glioma cells, depletion of Rac1 expression by siRNA strongly inhibits lamellipodia formation and results in a decrease in cell migration and invasion." (PMID 25243137, 2014). "The depletion of either Rac1 or synaptojanin 2, a Rac1 effector with phosphatidylinositol phosphatase activity, decreases invadopodia formation, and glioma cell invasion." (PMID 24109588, 2013). "For example, chemotherapeutic resistance in glioma cells has been shown to be promoted through Rac1-dependent Akt2 activity working upstream of the BCL2 family to promote cell survival." (PMID 24109588, 2013). "Functional evidence for the role of RhoA has been demonstrated under the inhibition of the RhoA effector ROCK, which led to activation of Rac1 in glioma cells and promoted invasion." (PMID 24109588, 2013). "The activation of Rac1 in neurotensin neuropeptide treated glioma cells was described in parallel with Cdc42 activity, although the dependence of one GTPase on the other for activation was not explored." (PMID 24109588, 2013).
glioma (continued). "Rac1 signaling has also been reported to be activated downstream of several known receptor drivers of glioma malignancy." (PMID 24109588, 2013). "Rac1 facilitation of glioma cell invasion occurs via signaling through several receptors and effectors." (PMID 24109588, 2013). "Cdc42 activation has also been demonstrated alongside Rac1 activation in GB cells downstream of PDGFRα association with SHP-2 non-receptor protein tyrosine phosphatase and Dynamin 2 (Dyn2) to promote glioma cell migration." (PMID 24109588, 2013). "Another member of the TNFRSF family, TROY, is overexpressed in glioma cells and activates Rac1 signaling in a Pyk-2 dependent fashion, leading to enhanced GB cell motility." (PMID 24109588, 2013). "Rac1 activation and promotion of cell migration and invasion in glioma is also seen downstream of signaling networks known to be utilized in neuronal signaling and development." (PMID 24109588, 2013). "In agreement with the published literature, we find that suppression of SFK activity with dasatinib in SF767 glioma cells inhibits p120 Y228 phosphorylation, Vav2 Y172 phosphorylation, and Rac1 activation, and blocks their directed migration in culture." (PMID 23457577, 2013). "In contrast, Vav3 expression is localized to the glioma cells and Vav3 was shown to mediate exchange for Rac1 in the promotion of glioma cell migration." (PMID 24109588, 2013). "Pyk2 and Rac1 have recently been reported to be involved in TROY expression in human glioma cell lines and both proteins are involved in cellular migration and invasion." (PMID 22649568, 2012). "Recently, Sema5A has been shown to suppress human glioma cell migration and invasion in a plexin-B3- and Rac1-dependent manner." (PMID 23050142, 2012). "The inactivation of Rac1 was confirmed to contribute to Sema5A-induced impediment of glioma cell migration and invasion, as evident by the abolishment of effect upon forced expression of a constitutively active Rac1 mutant." (PMID 23050142, 2012). "Since Rac1 is the major Rac isoform expressed in glioma cells, this assay essentially reports on the activation state of Rac1." (PMID 22966858, 2012). "A recent report that investigates the significance of Sema5A and plexin-B3 in glioma has also shown their suppression of Rac1 activation, though through a different mechanism." (PMID 23050142, 2012). "Silencing Sema3A expression by RNA interference resulted in a significant suppression in migration and an alteration in glioma cell morphology in a Rac1-dependent manner." (PMID 23050142, 2012). "Inhibition of ROCK induces glioma cell migration through Rac1 activation, suggesting that the relative degree of activation between RhoA and Rac1 regulates glioma cell movement." (PMID 24212955, 2011). "According to another study, PI3K/Cdc42 and PI3K/Rac1 pathways are important in LPA-mediated migration of glioma cells." (PMID 21943101, 2011). "In glioma cells, depletion of Rac1 expression by small interfering RNA reduces cell migration and invasion and strongly inhibits lamellipodia formation." (PMID 24212955, 2011). "In addition, in U-87 and LN229 glioma cells, 1A-116 selectively suppressed activation of RAC1 to guanine exchange factors including T-lymphoma invasion and metastasis-inducing protein 1 via interacting with the Trp56 residue." (PMID 40495887, 2025). "The Ras-related C3 botulinum toxin substrate 1 (Rac1)-WASP-family verprolin-homologous protein-2 (WAVE2)-actin-related protein 2/3 (Arp2/3) signaling pathway increases radiation resistance in U251 human glioma cells through CFL1." (PMID 39114368, 2024). "In the current study, we report that combination treatments that synergize with radiation in activating the immediate early response through the MAPK cascade upregulate the mevalonate pathway in vivo, thereby triggering repopulation of gliomas through prenylation of the Rho GTPase Rac-1." (PMID 38837899, 2024).
glioma (continued). "It was found to inhibit glioma cell invasion and migration by induction of Rac1 inactivation." (PMID 37627074, 2023). "Our emerging results suggest that the inhibition of Rac1 by 1A-116 may result in potential therapeutic benefits in glioma." (PMID 36230732, 2022). "TUNAR plays a tumor suppressive role in glioma cells by upregulating miR-200a and inhibiting Rac1." (PMID 32591022, 2020). "Findings regarding the role of Rac1 in glioma cell migration and invasion parallel those of Cdc42, for both, promote these two processes, bind to similar domains, are activated by common GEFs, and have the same intracellular location (at the front edge of the cell)." (PMID 32089990, 2020). "For example, it was reported that the functional complex of SEMA3C with its receptors NRP1/PLXNA2/PLXND1 could activate Rac1/NF-κB signaling to promote the survival and migration of glioma stem-like cells." (PMID 32640719, 2020). "Based on our experimental research, we hypothesized that NKCC1 promotes the EMT‐like process in gliomas via the RhoA and Rac1 signaling pathways." (PMID 30159893, 2019). "Additionally, invading glioma cells exhibit an increased Cdc42 and Rac1 activity, but a decreased activity of RhoA at the cell front, held responsible for the enhanced migration of leader cells." (PMID 31003495, 2019). "Therefore, we suggest that the NKCC1 promotes the EMT‐like process in gliomas via the RhoA and Rac1 signaling pathways." (PMID 30159893, 2019). "Here, we investigated whether NKCC1 promotes an epithelial–mesenchymal transition (EMT)‐like process in gliomas via the RhoA and Rac1 signaling pathways." (PMID 30159893, 2019). "Altogether, we were able to detect a cross-talk between sCPE, RPS6, Rac1 and glioma cell migration." (PMID 28978054, 2017). "We further analyzed whether there was a link between the mTOR-RPS6 axis and Rac1-signaling in human glioma cells." (PMID 28978054, 2017). "Additionally, sCPE diminishes glioma cell migration associated with a negative regulation of Rac1 signaling via RPS6, since both inhibition of mTOR and stimulation of Rac1 results in a reversed effect of sCPE on migration." (PMID 28978054, 2017). "Moreover, inhibition of Rac1 activity in glioma cells with a small molecule inhibitor represses proliferation through G1 arrest and induces apoptosis." (PMID 28160553, 2017). "In glioma, Rac1 is involved in stemness maintenance, surviving and apoptosis of GSCs." (PMID 27557508, 2016). "RAC1 is known to promote cell migration and invasion in glioma cells." (PMID 27556637, 2016). "Therefore, the downregulation of ARHGDIA regulates GTPase activity of Cdc42, Rac1, and RhoA, subsequently, increases Akt phosphorylation and leads to glioma cell proliferation and migration." (PMID 27726098, 2016). "A very recent study has demonstrated that Sema3C signaling could play a role as a central regulator of glioma stem cell survival and glioblastoma progression via activation of the Rac1/NF-κB signaling pathway." (PMID 26032848, 2015). "Our group previously showed that Rac1 is upregulated following WNK2 silencing in gliomas." (PMID 25596741, 2015). "The Rho family GEFs, VAV3 and Trio, regulate the invasive phenotype of glioma cells, and a recent study identified the two GEFs, Ect2 and Trio, as activators of various Rho GTPases including cdc42 and Rac1 downstream of Tweak and as regulators of cell migration." (PMID 25682201, 2015). "SEMA5A inhibits glioma cell migration through RAC1 inactivation." (PMID 24516532, 2014). "Rac1 has been shown to be important for the maintenance of stemness and tumorigenicity in human glioma, whereby depletion of Rac1 suppressed glioma stem-like cell migration, invasion, and malignant transformation, while conferring enhanced radiation sensitivity to these glioma stem-like cells." (PMID 24109588, 2013).
glioma (continued). "In addition, the phosphorylation of Dock180 at tyrosine 1811 has been demonstrated to occur downstream of PDGFRα in glioma, promoting Rac1 activation and cell invasion, migration, and survival." (PMID 24109588, 2013). "Rac1 is also thought to be important in glioma cell migration and invasion." (PMID 23457577, 2013). "Additionally, Rac1 activation at the plasma membrane in glioma is regulated by Geranylgeranyltransferase I as well as RLIP76 modulation of ubiquitination." (PMID 24109588, 2013). "Similarly, the PDGFRα receptor, which is amplified in a significant proportion of gliomas, induced Src-dependent Dock180 phosphorylation, with subsequent increased Rac1-GTP activity and GB cell growth and invasion." (PMID 24109588, 2013). "Rac1 has also been shown to regulate the formation of invadopodia, which are specialized formations of the plasma membrane that promote degradation of the extracellular matrix, an action critical in glioma cell invasion." (PMID 24109588, 2013). "Importantly, ELMO1, by forming the complex with dedicator of cytokinesis 180 (Dock180), serves as a Rac1 guanine nucleotide exchange factor that stimulates glioma cell migration and invasion." (PMID 22494416, 2012). "Indeed, we provide evidence that Rac1 inhibition by the 1A-116 molecule may be a feasible strategy to treat gliomas." (PMID 36230732, 2022). "It suggested KIF4A may regulate glioma cells growth and mobility through the Rac1/Cdc42 pathway." (PMID 36606197, 2022). "Finally, to implicate these downstream pathways in the regulation of the migration of glioma cells, we treated U87‐MG and SNB19 cells with small molecule inhibitors of Rho‐associated kinase (Y27632) and Rac1 (NSC23766) and assessed the effects on migration using a Transwell migration assay." (PMID 30159893, 2019). "Furthermore, in our GSC-like stemloid cell model, Rac1, 2 and 3 each plays a critical role in maintenance of stemloid cells with regard to their ability of proliferation and colony formation, suggesting their involvement in glioma progression." (PMID 28160553, 2017). "RhoG can also activate Rac1 and Cdc42 in the regulation of neuronal process plasticity, thus it remains a possibility that deregulated neuronal signaling and development pathways may also utilize RhoG to promote glioma malignancy." (PMID 24109588, 2013). "MAT has been previously documented in glioma cells, reducing Rac1 activity whilst increasing ROCK expression, and our previous studies have also highlighted phenotypic switching in glioma cells." (PMID 38804289, 2024). "Recently, ROCK1 is found as a novel Rac1 effector, and TRPV4 targets the AKT for phosphorylation, promotes migration and invasion through AKT/Rac1 signaling in glioma." (PMID 37369706, 2023). "For instance, in glioma, lncRNA XIST modulated RAC1 expression by functioning as a ceRNA of miR-137, which led to cell proliferation." (PMID 34771549, 2021). "Through a Rictor/mTOR2/RAC1/WAVE2 axis, these IDH1-mutant glioma cells overcome metabolite depletion by endocytosing beneficial ECM material, promoting tumor resistance." (PMID 32545340, 2020). "The downregulation of Rho GTPase-activating protein 15 (ARHGAP15), a Rac1-specific GAP, has been observed in glioma and pancreatic ductal adenocarcinoma." (PMID 29867200, 2018). "In Glioma, XIST increases Rac-1 signaling by sequestering miR-137, in colorectal cancer, it increases MAPK1 signaling by sequestering miR-132-3p or by sequestering miR378, which targets MAPK1 in prostate." (PMID 30555629, 2018). "Seven Rho GTPases (RND1, RND3, RAC3, RHOA, RAC2, RAC1 and RHOC) showed a significantly greater connectivity in grade IV glioma and seven (CHP, RHOD, RHOF, RHOB, RHOQ, RND2, RHOBTB3) showed greater connectivity in grade II glioma." (PMID 26132659, 2015).